CXCR4 (C-X-C motif chemokine receptor 4)
Diseases named in the same sentence as CXCR4 in open-access papers (continued):
Sharing a sentence is not in itself a finding about the gene and the disease.
breast carcinoma (continued). "In our study, we showed that losartan could decrease both CXCR4 in primary tumors and SDF-1α in lymph nodes, which is an essential mechanism for reducing lymph node metastasis in breast cancer." (PMID 31219799, 2019). "However, findings from tumor research show that CXCL8 stimulation upregulates CXCR4 levels in prostate carcinoma cells and CXCR4 drives tumor invasion and metastasis via activating CXCR2 in breast cancer." (PMID 31885605, 2019). "The results confirm our recent study where we found that cats with CXCR4 positive PT exhibit significantly lower serum CXCL12 levels than cats with CXCR4-negative mammary carcinomas." (PMID 30012106, 2018). "In order to provide a deeper insight into the role of the CXCR4/CXCL12 axis in FMC, CXCR4 and CXCL12 expression was analyzed and quantified in PT, RM and DM from female cats with mammary carcinoma and its expression was correlated with blood serum CXCL12 levels and molecular subtypes." (PMID 30012106, 2018). "The present study demonstrated that lncRNA SPRY4-IT1 promoted breast cancer cell biological activity, whereas NT21MP could inhibit its effect by SDF-1α/CXCR4 pathway, which was partially through SKA2." (PMID 30104400, 2018). "To date, reports on CXCL12 and CXCR4 expression in the Indonesian population have only come from studies of patients with breast cancer, but not yet from patients with CRC." (PMID 29887884, 2018). "Such SDF-1/CXCR4-dependent vasculogenesis has been demonstrated in mouse models of several tumor entities, such as GBM, HNSCC, lung adenocarcinoma, hepatocellular carcinoma or breast cancer." (PMID 30622535, 2018). "We proceeded to simultaneously assess the potential apoptotic activity of all these compounds, including AMD3100, IT1t, MSX-122, TIQ-15 and compounds 1-8 in MDA-MB-231 cells versus the CXCR4 negative MDA-MB-468 breast cancer cells." (PMID 29682200, 2018). "CXCR4 was more expressed in PT than in metastases (p = 0.0067), whereas CXCL12 was highly expressed in metastatic lesions located in liver and lung (p < 0.0001), as reported for human breast cancer." (PMID 30012106, 2018). "Furthermore, expression of CXCR4 and CXCL12 predicts lymph node metastasis in colorectal, esophageal and breast cancer." (PMID 29305742, 2018). "This phenomenon was selective for CXCR4 positive breast cancer cells and the viability of both Jurkat and CXCR4 negative MDA-MB-468 cells was not compromised upon exposure to high concentrations of any of the antagonists studied (10 μM)." (PMID 29682200, 2018). "So far, data regarding the involvement of the CXCR4/CXCL12 axis in FMC revealed that CXCR4 is overexpressed in the majority of FMC with frequent metastization at lymph node, liver and lung as reported in human breast cancer." (PMID 30012106, 2018). "Moreover, co-expression of both receptors, CXCR4 and CXCR7, has shown to inhibit the invasive properties of breast cancer cells." (PMID 29920526, 2018). "In conclusion, CXCR4-targeted PET imaging of primary and recurrent breast cancer is feasible." (PMID 30191351, 2018). "CXCR4, a seven-transmembrane G-protein-coupled receptor for stromal-cell derived factor-1α (SDF-1α), has been shown to be expressed in human breast cancer cells, and activation of the SDF-1α/CXCR4 axis is important in breast cancer migration and metastasis." (PMID 29599799, 2018). "The receptor CXCR4 and its ligand CXCL12 play crucial roles in breast cancer." (PMID 30012106, 2018). "The discovery that cancer cells overexpress the chemokine receptor CXCR4 and that its blocking can inhibit metastasis to organs that express its ligand, the chemokine CXCL12, opened new therapeutic avenues for the targeting of metastatic breast cancer." (PMID 30441765, 2018). "While feline CXCR4 is significantly more expressed in PT, CXCL12 is highly abundant in distant metastatic organs such as liver and lung, as it has been observed for woman breast cancer." (PMID 30012106, 2018).
breast carcinoma (continued). "Although PDGF signaling is implicated in the TGF-β-mediated epithelial mesenchymal transition of tumor cells, the role of PDGF receptors in the SDF-1α/CXCR4 activation of breast cancer has not been investigated." (PMID 28415580, 2017). "Additionally, miR-381 inhibited breast cancer cells proliferation, EMT and metastasis by targeting CXCR4." (PMID 28415580, 2017). "From the 42 feline mammary carcinomas evaluated, 6 (14%) samples were classified as CXCR4-negative samples and 36 (86%) as CXCR4-positive samples, with CXCR4-negative mammary carcinoma showing significant higher serum SDF-1 levels (p=0.027)." (PMID 29285291, 2017). "Given that BAG3 might regulate CXCR4 in breast cancer, real-time PCR was performed to evaluate the relationship between BAG3 and CXCR4." (PMID 28703799, 2017). "Additionally, it has been found that EMT program promotion, by the increased HIF-1α and TGF-β signaling, induced over-expression of CXCR4 and VEGF in breast cancer cells collaborated in their diffusion and secondary bone involvement." (PMID 29099748, 2017). "Also, it is intriguing that GRK3 not only controlled survival and proliferation of breast cancer cells but also promoted primary breast cancer invasion and metastasis by dysregulated signaling through CXCL12/CXCR4." (PMID 29445249, 2017). "CXCR4 and its ligand CXCL12 (also named stromal cell-derived factor 1, SDF-1) have been shown to be consistently expressed in human breast cancer cells, and the activation of SDF-1α/CXCR4 axis has found to play a key role in breast cancer migration and metastasis." (PMID 28446538, 2017). "The CXCR4/CXCL12 receptor/ligand pair has been shown to have a critical role in the progression of many kinds of cancers, including lung cancer, colon cancer, ovarian cancer, melanoma, leukemia 30 and breast cancer." (PMID 29263923, 2017). "In particular, CXCR4 stimulation was found to induce expression of vascular endothelial growth factor (VEGF) in human breast carcinoma cells and conversely blockade of CXCL12/CXCR4 signalling was able to suppress tumour angiogenesis and tumour growth in vivo in a murine model." (PMID 28332618, 2017). "We also identified PDGFRα as an effector that mediates CXCR4-induced EMT, suggesting that targeting the CXCR4-PDGFRα-PI3K pathway may be beneficial to NT21MP-reversed drug resistance in breast cancer." (PMID 28415580, 2017). "Considering the proliferative role of SDF-1/CXCR4 axis in breast tumors and the promising in vitro results obtained with CXCR4 inhibitors, the expression of the SDF-1 receptor was also evaluated in feline mammary carcinomas." (PMID 29285291, 2017). "In addition, human epidermal growth factor receptor 2 (HER2) enhances the expression of C–X–C motif chemokine receptor 4 (CXCR4), which is required for HER2-mediated invasion and metastasis of breast cancer." (PMID 28356139, 2017). "Furthermore, microarray data profiling of invasive human breast cancer tissues downloaded from GEO and TCGA database was applied to examine the co-expression of KLF8 and CXCR4." (PMID 26993780, 2016). "Our data showed overexpression of proinflammatory factors including CXCL1, CXCL2, CXCR4, CCL3, CCL4, IL-8, and PTGS2/COX-2 in the peripheral blood of patients with breast cancer both when considering the subtypes individually and when considering all breast cancer samples as a group." (PMID 26884644, 2016). "Interestingly, CXCR4 ligand CXCL12/SDF-1α is prominent in bone marrow stromal cells with studies showing that CXCR4 cooperatively with other factors such as IL-11, CTGF and OPN facilitate osteolytic bone metastasis in breast cancer MDA-MB-231 cells." (PMID 27590724, 2016). "Thus, the identification of KLF8 as a critical feed-forward inducer of CXCR4 expression and activation of FAK in breast cancer cells presents an excellent therapeutic target to correct aberrant signaling of both FAK and CXCR4 specifically in cancer cells." (PMID 26993780, 2016).
breast carcinoma (continued). "No change of CXCR4 expression was found in our trastuzumab-resistant breast cancer cells (data not shown)." (PMID 26621843, 2016). "Furthermore, being consistent with TSHZ2-mediated suppression of CXCR4 expression, we found that CXCL12-induced breast cancer cell migration was inhibited by the expression of TSHZ2 but neither LacZ nor TSHZ2del4." (PMID 26744317, 2016). "In breast cancer, the FOXP3 has been described as a transcriptional repressor of genes involved in tumor development, like HER2 and SKP2, and also in cancer progression, like CXCR4." (PMID 27830498, 2016). "Therefore, we evaluated PPARγ expression in MCF-7 and MDA-MB-231 breast cancer cells and assessed the effects of BRL on CXCR4 expression at both protein and mRNA levels in both cell lines." (PMID 27556298, 2016). "We investigated the expression level of CXCR4 in the three breast cancer cell lines, namely SK-BR-3, MDA-MB-435s and MDA-MB-231, and found that CXCR4 protein expression was down-regulated by the TPD7 in a dose-dependent manner at the concentrations used in the experiments." (PMID 25753200, 2015). "The expression level and cellular localization of CXCR4 in human breast tumours have also been analyzed in view of its molecular subtypes, including triple-negative breast cancers (TNBC), luminal subtypes, and HER2-positive breast cancers, via IHC." (PMID 26161302, 2015). "Furthermore, we revealed that GLI1 up-regulated the expression of CXCR4, CXCR7, and LCP1 to enhance the CXCL12-induced ERK phosphorylation and migration of breast cancer cells." (PMID 26413813, 2015). "There are opposing reports in the literature regarding the expression of CXCR4 in breast cancer stating that it is increased, decreased, or not changed compared to benign epithelium." (PMID 26161302, 2015). "It has been shown that CXCR4/SDF-1α interactions induced increased migration, proliferation and adhesion of breast cancer cells through different signaling pathways such as calcium mobilization, phosphorylation of src and fak, and phosphatidylinositol 3-kinase." (PMID 26231656, 2015). "Based upon these results, TPD7 might be promising candidate as CXCR4 inhibitor, the data supported further development of TPD7 as an adjuvant therapy agent for breast cancer." (PMID 25753200, 2015). "These evidences indicated a role of GLI1 in enhancing the CXCL12/CXCR4/CXCR7 signaling axis, which may be responsible for tissue-specific metastasis of breast cancer cells." (PMID 26413813, 2015). "Recently, a growing body of evidence has been presented to show that SDF-1α/CXCR4 stimulation also leads to the secretion of various proteases, such as MMP-2 and MMP-9 by the breast cancer cells, which are then used to degrade the extracellular matrix, thereby facilitating cellular motility." (PMID 25753200, 2015). "Because the reduced expression of CXCR4 by TPD7 was irrespective of HER2 status in breast cancer, we used two of these cell lines, MDA-MB-435s and MDA-MB-231, to gain insights into the mechanisms of TPD7 on down-regulation of CXCR4 in further studies." (PMID 25753200, 2015). "As self-renewal of human and animal mammary cancer stem cells involves a diverse network of regulatory mechanisms, including the signaling pathways of EGFR, CXCL12/CXCR4 and ER-alpha, we analysed whether these proteins are expressed in CMC cultures." (PMID 25884842, 2015). "For interaction studies, we chose MCF-7 breast cancer cells, since they highly express CXCR4 and CXCR7 at the protein level but not CXCR3 (another target for CXCL11)." (PMID 24770893, 2014). "In addition, CXCR4, the receptor for chemokine stromal cell derived factor 1α (SDF-1α), has been reported to mediate homing to bone in prostate and breast cancer cells." (PMID 24587095, 2014). "Our findings suggest that CXCR4 and CXCR7 closely interact in breast cancer cells." (PMID 24770893, 2014).
breast carcinoma (continued). "The expression profiles of CXCL12, CXCR4 and CXCR7 in breast cancer biopsies are almost identical to that obtained when we overexpressed COUP-TFI in MCF-7 cancer cells, suggesting that our in-vitro results might have a clinical relevance." (PMID 24906407, 2014). "Downregulation of one particular miRNA, miR-139, might promote gastric tumour progression and metastasis via upregulating CXCR4, Bao and cols suggest that miR-139 might be suppressed by upstream HER2 signaling, a strongly deregulated pathway in breast cancer." (PMID 25047087, 2014). "This signaling pathway, which is composed of the chemokine CXCL12 (also called SDF-1 for stromal cell-derived factor 1) and its receptors CXCR4 and CXCR7, play pivotal roles in the cell migration, angiogenesis, proliferation, and survival of many cancer cells, including breast cancer." (PMID 24906407, 2014). "Reactivation of CXCR4 by AZA and/or TSA has been previously demonstrated also in four pancreatic cancer cell lines (AsPC1, BxPC3, Capan1, Capan2, CFPAC1, and MiaPaCa2) and two breast cancer cell lines (MCF-7 and ZR-75-1)." (PMID 25114911, 2014). "In addition to CXCR4, breast cancer cells express another chemokine receptor, CXCR7, which binds to CXCL12 with greater affinity than does CXCR4." (PMID 24886617, 2014). "CXCR4, one of the well-characterized chemokine receptors expressed in breast cancer cells and attracted by its ligand, SDF-1α, is critical in the targeted metastasis of breast cancer." (PMID 23710200, 2013). "Here, we report that AMD3465 triggers a reduction in breast cancer cell invasiveness in vitro, and promotes marked changes in oncogenic signaling proteins including a reduction in STAT3, JAK2, AKT, and CXCR4 phosphorylation and the reduced expression of GSK3 and cMYC." (PMID 23484027, 2013). "Melanoma shares a similar metastatic phenotype to breast cancer, which also expresses high levels of CXCR4 and CCR7, but unlike breast cancer, experiences frequent metastasis to the skin." (PMID 24259307, 2013). "Additionally, breast cancer cell lines exhibit different levels of Chemokine (C-X-C motif) Receptor 4 (CXCR4), which appears to positively correlate with both CSC proportions and the propensity of breast cancer cell lines to metastasize." (PMID 22295241, 2012). "Third, BMSC expression of Sdf1, a major cytokine promoting breast cancer cell migration, was unaffected by ISO treatment for 2, 6, or 24 h; in breast cancer cells treated with ISO, the expression of RANK and CXCR4—the receptors for RANKL and SDF1, respectively—remained unchanged as well." (PMID 22815651, 2012). "Muller and colleagues have shown that chemokine receptors CXCR4 and CXCR7 are highly expressed in human breast cancer specimens, while their corresponding ligands CXCL12/SDF-1alpha (stromal cell-derived factor) and CCL21/6Ckine showed peak levels in primary breast cancer destination sites." (PMID 22746994, 2012). "A functional linkage of the structurally unrelated receptors HER2 and CXCR4 has been suggested for breast cancer but has not been evaluated for esophageal carcinoma." (PMID 23082154, 2012). "CXCR4 and its ligand SDF-1α play an important role in targeting breast cancer metastases." (PMID 23082154, 2012). "Administration of the monoclonal antibody to CXCR4 to SCID mice was found to effectively regress lung metastasis from MDA-MB-231 xenografts, indicating the key roles of chemokines and chemokine receptors in the organ-specific metastasis of breast cancer." (PMID 23181100, 2012). "CXCR4 overexpression has been identified as a negative prognostic marker in a various type of cancers, such as breast cancer, colorectal cancer and lung cancer." (PMID 23071744, 2012). "Overexpression of chemokines - especially of CXCR4 and CCR7 - was observed in breast cancer cells and surgical specimens, but chemokine receptors are also highly expressed in other tumour types including cancers of epithelial, mesenchymal and hematopoietic origin." (PMID 22253872, 2012).
breast carcinoma (continued). "Together, these results suggest that the epigenetic regulation by DNA methylation of both the CXCR4 and CXCL12 genes in breast cancer could serve as a potential biomarker to indicate patient prognosis." (PMID 22220212, 2011). "In the present study, we have analyzed the effects of synthetic non-psychoactive cannabinoid JWH-015 that specifically binds to CB2 receptors on breast cancer and have shown that this compound inhibits CXCL12/CXCR4-induced breast cancer invasive properties in vitro." (PMID 21915267, 2011). "A viable pathway illustrating the role of CXCR4 in breast carcinoma migration from the primary site does not explain how these cells are guided to axillary lymph nodes." (PMID 22295222, 2011). "Using immunohistochemistry, CXCR4 was detected in both breast cancer cell lines as well as normal mammary tissue." (PMID 22295222, 2011). "We found that plumbagin downregulated the expression of CXCR4 in breast cancer cells irrespective of their HER2 status." (PMID 21880153, 2011). "To examine whether the CXCL12 signaling axis may be differentially regulated by ER ligands in breast cancer cells, we examined the effects of several xeno-estrogens on the expression of CXCL12, CXCR4 and CXCR7 in MCF-7 cells." (PMID 21695171, 2011). "Our results demonstrate, for the first time, that plumbagin can downregulate CXCR4 expression in various tumor cells, including HER2-overexpressing breast cancer cells, and this could be through its inhibition of NF-κB activation." (PMID 21880153, 2011). "The CXCR4, CCR7, CXCL12, CCL21, and EGFR biomarkers were analyzed along with ER, PR, and HER-2/neu in breast cancer tissue microarray (TMA) specimens, including 200 primary breast cancer specimens by immunohistochemistry." (PMID 20181250, 2010). "Therefore, we would propose that treatment with CXCR4 antagonists such as AMD3100 in the perioperative period would prevent the migration and invasion of CXCR4 expressing breast cancer cells into organs of metastases that are rich in SDF1α." (PMID 20492653, 2010). "Moreover, as staining for CXCL12 and CCL21 (or CXCR4 and CCR7) was tightly linked in the group of primary tumors and lymph node metastasis tumors in this study, it is likely that a shared mechanism may account for variations in expression levels of both molecules in breast cancer." (PMID 20181250, 2010). "Adjustment for CD4+ cell count, HIV viral load, and use of antiretroviral therapy did not attenuate the association between infection with CXCR4-tropic HIV and breast cancer." (PMID 21179547, 2010). "Breast cancer cells lacking expression of CXCL12 but exhibiting CXCR4 can metastasize to target organs that secrete CXCL12." (PMID 20830311, 2010). "Cytoplasmic reactivity of CXCR4 correlated positively with lymph node metastasis of breast cancer (P < 0.001), but not with the amount of involved lymph nodes." (PMID 20181250, 2010). "To define the role of melatonin in breast cancer cell invasion and metastasis, we used three invasive breast cancer cell clones that were derived from the parental MCF-7 cells - the MCF-7/6, MCF-7/Her2.1, and MCF-7/CXCR4 cells - instead of using the poorly invasive MCF-7 breast cancer cells." (PMID 21167057, 2010). "Linking HIV with breast cancer was the observation that programmed cell death (apoptosis) was induced in human breast cancer cell lines through binding of CXCR4-tropic, but not CCR5-tropic, HIV envelope protein." (PMID 21179547, 2010). "Stimulation of HDMECs with CXCL12 enhanced adhesion selectivity of circulating breast cancer cells by a comparable amount, regardless of expression of chemokine receptors CXCR4 or CXCR7 on cancer cells." (PMID 19484126, 2009). "Surprisingly however, we have found that DIMand genistein downregulate CXCR4 and CXCL12 in both ER+ and ER− cell lines,indicating that these phytochemicals may be effective in the treatment of bothearly- and late-stage breast cancers." (PMID 19325924, 2009).